IL4 (interleukin 4)
Diseases named in the same sentence as IL4 in open-access papers (continued):
Sharing a sentence is not in itself a finding about the gene and the disease.
infection (continued). "Prior studies examining the TFH response after infection with the nematode Nb showed that TFH cells change over time following infection and proceed from producing IL-21 alone (TFH21 cells) to producing primarily IL-4 (TFH4 cells)." (PMID 37575256, 2023). "In contrast, depletion of Gr1+ cells did not affect the frequency of CD4+ IL-4+ (Th2) cells but significantly increased this T-cell subset at week 2 of infection." (PMID 36776848, 2023). "At week 4 post infection, CD4+ T-cells showed a mixed response to S. mansoni AWA by secreting cytokines which encompassed Th1 (IFNγ, TNFα, IL-2 & IL-1β), Th2 (IL-4, IL-5, IL-13) and regulatory responses (IL-10) as well as the regulatory T cell transcription factor Foxp3." (PMID 37837930, 2023). "This indicates that indeed the L-arginine metabolism is responsible for microbicidal macrophage activity and that IL-4 per se has no toxic effects during infection." (PMID 37190073, 2023). "In addition, although the transcription of various cytokines, such as IL-1β, IL-2, IL-4, IL-8, and IL-10, was shown to be highly upregulated to defend the organism against DHAV-(1/3) infection, the variation of duck IL-22 after DHAV infection is still unclear." (PMID 37391858, 2023). "Neither infection with Mtb nor treatment with hSAA-1 induced the expression of Th2 cytokines in MDMs, namely IL-4 and IL-13, which polarize macrophages to an M2 activation status." (PMID 37781389, 2023). "Infection of THP-1 cells with fdr mutants resulted in increased IL-1β, TNF-α, and IL-4." (PMID 37764917, 2023). "The results showed that the protein concentration of inflammatory cytokines in both types of mice was significantly increased after BMA8 strain infection, and the expression of cytokines was higher in BALB/c mice, including IL-2, IL-4, IL-6, IL-10, IL-12p70, KC/GRO, IFN-γ and TNF-α." (PMID 37081549, 2023). "In this current study the influence of IL-4- and IFNγ-dependent polarisation (pre-stimulation) or stimulation of non-polarised (post-stimulation) macrophages upon infection with Salmonella enterica serovar Typhimurium was analysed." (PMID 37190073, 2023). "Infection of neutrophils and HL-60 cells produce striking quantities of chemokines, including IL-8, RANTES, MIP1α, MIP1β, and MCP1, but not other cytokines observed with in vivo infection, including IFNγ, IL-10, TNFα, IL1β, or IL4." (PMID 37228668, 2023). "After infection with coxsackievirus B3, CD4+ T cells from male animals predominantly produced the Th1 cytokine IFN-gamma, whereas those from females produced the Th2 cytokine IL-4." (PMID 38140610, 2023). "In contrast, greater production of IL-4, IL-13, IL-9, and IL-2 was observed following drug treatment irrespective of infection status, consistent with the observation of increased Th2 populations at the PDTB stage." (PMID 37898618, 2023). "Furthermore, the IL-4 driven inability of BALB/c mice to control Leishmania infections was shown to be confined to young animals, whereas old mice controlled the infection, partially depending on elevated IL-12 production by macrophages in aged mice." (PMID 35690651, 2022). "It is important to note that in the fight against infection by pathogens such as parasites, Th1 (with its primary cytokine, IFN-γ), Th2 (with its main cytokine, IL-4), Th9 (with its main cytokine, IL-9) and Th17 (with its main cytokine, IL-17) immune responses play a vital role." (PMID 35933400, 2022). "Our results show that ILC2 do not expand in response to L. major infection and are not a predominant source of IL-4 during the first 5 to 6 days of infection." (PMID 35894051, 2022). "Our results showed that the concentrations of IL-4 and IL-10 in Co-PRRSV-PCV2 and PRRSV-PCV2 groups were significantly higher than the other groups, suggesting that adaptive immune responses were robust in these infection groups." (PMID 35215787, 2022). "At day 5 to 6 post infection, we observed an upregulation of IL-4, but not of IL-5, IL-10 or IL-13 mRNA." (PMID 35894051, 2022).
infection (continued). "Furthermore, in macrophages, lincRNA-MIR99AHG is translocated to the nucleus and interacts with high affinity to hnRNPA2/B1 following IL-4/IL-13 stimulation and Mtb HN878 infection." (PMID 35895506, 2022). "IL-10, IL-7, and IFN-γ all maintained a stable expression over time and could be playing a role in longer-term immunity, but IL-1RA, MIP-1α, IL-4, TNF-α, and more were all significantly decreased one-year post-infection compared to levels at discharge." (PMID 35406717, 2022). "Overall, the results indicate that Omp16 did not affect IFN-γ, TNF-α and IL-4 secretion during infection by B. suis." (PMID 34675138, 2022). "In the cortex of adult mice exposed to JWH-018 as adolescents, we found an increasing trend in IL4 levels and an increase in RANTES, a chemotactic cytokine that directs leukocytes to sites of inflammation and infection, along with a decrease in IL2 and IL13 expression compared to vehicle mice." (PMID 35943523, 2022). "The number of IL-4+SiglecF− cells per ear was small, did not increase upon infection with L. major and consisted mostly of mast cells and basophils (C. Sasse, data not shown)." (PMID 35894051, 2022). "Knockdown of MIR99AHG by ASOs significantly reduced the intracellular Mtb growth in IL-4/IL-13 stimulated macrophages at 72 h post Mtb HN878 infection but did not change the phagocytic ability of macrophages to uptake Mtb at 4 h postinfection." (PMID 35895506, 2022). "However, a predominant Th1 immune response is also observed in DL, as well as in subjects with SC infection, due to elevated IFN-γ levels compared to IL-4." (PMID 35456141, 2022). "We also studied the expression of ILC2-activating and ILC2-inhibiting cytokines following infection and tested whether ILC2 are early IL-4 producers during L. major infection." (PMID 35894051, 2022). "Interleukin (IL)-4 plays a central role in the initiation of a type 2 T helper cell (Th2) response, which leads to non-healing and progressive infections with the protozoan parasite Leishmania (L.) major." (PMID 35894051, 2022). "On the other hand, anti-inflammatory cytokines interleukin-13 (IL-13), interleukin-4 (IL-4), interleukin-10 (IL-10) and transforming growth factor-β (TGF-β) appear on the fourth day after infection and ameliorate the exacerbation of inflammation and participate in the healing of lesions." (PMID 35053737, 2022). "As only a small fraction of CD45+SiglecF− cells expressed GFP in both C57BL/6 and BALB/c 4get mice, we conclude that eosinophils rather than ILC2 account for the observed increase in IL-4 expression early after infection with L. major." (PMID 35894051, 2022). "Although CD11c depletion at this stage of infection resulted in impaired liver cell potential to produce IL-4 and IL-10, it did not significantly impact Ag-specific cytokine responses." (PMID 35958580, 2022). "Altogether, these data show that MIR99AHG expression varies according to the macrophage polarization state; in IL-4/IL-13 polarized macrophages MIR99AHG expression was induced, while the expression of MIR99AHG was downregulated following Mtb HN878 infection and in active TB patients." (PMID 35895506, 2022). "The difference was that IL‐10 was significantly higher than the control group at 30 days after infection, but IL‐4 was not." (PMID 36169259, 2022). "IL-4 and IFN-γ can induce the production of antibodies in B cells, as well as attract and activate immune cells, such as macrophages and other lymphocytes, at infection sites." (PMID 35820892, 2022). "Comparison of the CFU counts at 48 hours post-infection showed that IL-17RA-/- mice and asthmatic mice, but not TNFR1α-/-, IL-4-/- and IFNγR-/- mice, lose control of early B. melitensis infection." (PMID 35771771, 2022). "Treatment of undifferentiated keratinocytes with IL-4/13 did not enhance either the infection (plaque formation) or the amount of virus recovered from cells." (PMID 35456017, 2022).
infection (continued). "Another interesting observation is that the severity of infection and histopathology influenced by infection was significantly reduced in the absence of IL-4." (PMID 34226412, 2021). "Previous studies using the N. brasiliensis model in IL-4Rα–deficient animals or IL-4/IL-13-double–deficient mice did not distinguish between the relative roles of IL-4 and IL-13 during infection." (PMID 34127548, 2021). "Levels of IL-4, IL-5, and IL-6 were not significantly elevated in any infection group versus mock infection." (PMID 34202420, 2021). "Thus, these IL-4 regulatory mechanisms, particularly the role of STAT3, warrants further investigation in the context of infection/vaccination." (PMID 34006897, 2021). "In the absence of IL-4 we found that the levels of IFNγ in pup lungs were not different than in the lungs of P. murina-infected C57BL/6 wild type pups after day 21 post-infection." (PMID 34682248, 2021). "Peripheral immune response dynamics were similar after the infection with both isolates, with a significant increase in the percentage of CD4+ T cells at 6 and 9 dpi in PBMC, coincident with the higher levels of IFN-γ and IL-4 release." (PMID 34239816, 2021). "The influx of the inflammatory cells also peaked with increasing numbers of macrophages, neutrophils, and dendritic cells which suggested that the absence of IL-4 reduces infection-induced pulmonary inflammation." (PMID 34226412, 2021). "We have also found the type-2 polarizing cytokine IL-4 is not sufficient to replicate infection induced metabolic reprogramming." (PMID 33417618, 2021). "The mRNA expression levels of type 1 and 2 cytokines, i.e., interferon (IFN)-γ [NM_008337], interleukin (IL)-4 [NM_021283], IL-5 [NM_010558], and IL-13 [NM_008355], were not altered by larval infection." (PMID 34081755, 2021). "iPathway analysis (Advaita) of the transcriptome of IL-4 injected HFD ApoE-/- mice suggested a distinct transcriptional landscape from what is induced by S. mansoni infection with infection modulating more genes in metabolic pathways of BMDM than IL-4c injection." (PMID 33417618, 2021). "The percentages of IL-4+, IL-5+, IL-6+, IL-21+, IL-1α+, and IL-17+ γδT cells were increased (p < 0.05), but the percentage of IFN-γ-expressing γδT cells decreased (p < 0.05) post-infection." (PMID 33588839, 2021). "Assessment of thoracic (lung draining) lymph node T cell responses during schistosomula lung migration revealed a significant increase in Th2 cell IL-4 expression, but not Th1 cell IFNγ, at days 14 and 21 post 70 cercariae infection." (PMID 33953712, 2021). "However, following treatment among children with natural infection in this cohort, PBMC stimulation in response to SWAP and SEA resulted in significant increases in the production of IL-4, IL-5, IL-10, and IL-13 compared to uninfected children." (PMID 33861768, 2021). "However, infection with USA300 did trigger increased production of cytokines and chemokines related to severity, including IFNy, GM-CSF, TNFa, IL-4, and IL-6." (PMID 33573328, 2021). "In particular, TLR3 might act via IRF3, producing interleukin (IL)-1α, IL-1β, IL-4, IL-6, and IFN-α and IFN-β, during the first 24 h post-infection." (PMID 34576716, 2021). "Injection of IL-4 complexes to simulate the induction of IL-4 by egg antigens, failed to recapitulate the infection induced reprogramming of macrophage respiration." (PMID 33417618, 2021). "Group comparisons for differential gene expression in lung homogenates showed no significant change in the induction of IL-4 or IL-5 in the mRNA groups compared to buffer or mock infection groups (data not shown)." (PMID 33863911, 2021). "Overexposure of either neonatal or adult mice to IL-4 during primary infection does not, however, suppress the total amount of RSV-specific antibody generated, suggesting IL-4 signaling is not the key signal dysregulating TFH after early-life infection." (PMID 34665220, 2021).
infection (continued). "Based on these data, we hypothesize that the presence of immunoregulatory cytokines, such as IL-4 and IL-13, and alternatively activated macrophages and MDSC during resolution of infection may play a protective role in the postnatal developing lung." (PMID 34682248, 2021). "During in vivo infections by L.a. parasites, a mix of different CD4 T cell responses is observed (Th1, Th2), in addition to the presence of other cell types such as NK cells and ILC2, which can produce IFN-γ or IL-4 for instance." (PMID 34557194, 2021). "We also failed to see IL-13 compensate for the lack of IL-4 and in fact IL-13 was lower in the lungs of IL-4−/− pups at day 30 post-infection as compared to wild type pups." (PMID 34682248, 2021). "It is clear from the data shown that though the IL-4 bias effects the characteristics of the neonatal immune response to P. murina, IL-4 does not effect the ability of neonatal mice to clear infection." (PMID 34682248, 2021). "In addition, LP 3% mice showed decreased levels of cytokines IL-4 and IFN-γ in liver homogenate 50 days after infection by S. mansoni compared to the Ctrl group." (PMID 33815321, 2021). "In contrast, the expression of IL-4 and PGER4 in peritoneal cells from C57BL/6 mice was moderately increased on day 5 post-infection, while IL-4 was the only overexpressed gene on day 30 post-infection." (PMID 33928043, 2021). "To investigate the responding CD4+ T cell repertoire and response to helminths, we infected IL-44get reporter mice with the helminth N. brasiliensis and performed TCRβ sequencing on sorted IL-4-expressing CD4+ T cells from the lung and lung-draining mediastinal lymph nodes nine days after infection." (PMID 34106992, 2021). "Significantly higher amounts of IFNγ, IL-4, and GM-CSF were observed in the rAd5-YFV trivalent vaccine-immunized mice when compared to animals vaccinated with the rAd5-LcrV monovalent vaccine in response to infection." (PMID 33514747, 2021). "Our data showed no increase in circulating TNF levels in LP 3% mice upon infection, and, although we have not measured IL-13 levels, studies demonstrated that the level of this cytokine is lower in the absence of IL-4." (PMID 33815321, 2021). "In contrast, in the infected control group, IL-2, IL-4, IL-6, and IL-17a levels rose slowly and did not change significantly after day 21 post-infection." (PMID 33717108, 2021). "However, IL-4 and TNF-α levels were decreased in the spleen of neutropenic animals 1-day post infection." (PMID 34642440, 2021). "In our study, we found that ΔADSL-immunized mice produced higher levels of IL-12, IFN-γ, and IL-4 at 30 and 70 days post-infection than non-immunized mice." (PMID 31935935, 2020). "At the infection site, we detected a small production of IL-10, but we were unable to detect production of either IL-4 or interferon-γ, indicating resolution of infection without effect on the percentage of regulatory T cells." (PMID 32867857, 2020). "Our results showed that the hippocampus of TB mice exhibited a highly significant increase in the expression of the pro-inflammatory (TNFα, IFNγ, IL12) and anti-inflammatory cytokines (IL4, TGFβ), as well as the enzymes iNOS and IDO from day one post-infection." (PMID 33322180, 2020). "In this study, the concentrations of serum IL-4 and TGF-β in the immunized group and the infection group were both increased after L3 challenge, the concentrations in the nonimmunized and uninfected group (group 3) were still lower even when they were injected with adjuvant." (PMID 31935869, 2020). "By comparing the levels of IL-4 and TNF-α in the control and vaccinated groups post-infection, it was found that the vaccines might regulate the Th1 and Th2 responses to perform the leishmanicidal actions." (PMID 32176727, 2020). "In the present study, no production of IFN-γ or IL-4 was detected at the site of infection after treatment with either combination therapy or meglumine antimoniate alone." (PMID 32867857, 2020).
infection (continued). "The PBMC were capable of producing IL-4 as demonstrated by ConA stimulation indicating that IL-4 is not a major component of the ovine immune response to C. abortus irrespective of a mucosal or parenteral route of infection." (PMID 32487248, 2020). "IL‐4–deficient or IL‐4Rα–deficient BALB/c mice, harbour similar numbers of worms as WT BALB/c mice late in infection indicating that IL‐4 is not responsible for killing of adult worms in this strain." (PMID 32145033, 2020). "There were no significant increases in IL-4, IL-5, or eosinophilic cationic protein following infection (data not shown)." (PMID 32283204, 2020). "At 48 h post-infection, both IL-4-primed M2 cells and non-polarized M0 cells contained significantly increased loads of bacteria (determined by the copy number of Orientia 47-kDa gene) than LPS-primed M1 cells (p < 0.0001)." (PMID 32119672, 2020). "Wild type and LmarLBV1-depleted L. (M.) martiniquensis were used to infect non-stimulated, classically (LPS/IFN-γ), or alternatively (IL4) stimulated primary murine macrophages to assess early stages of infection." (PMID 32024293, 2020). "As IL-4 is a critical cytokine observed throughout the pathogenesis of F. hepatica infection, the appearance of an abundant population of alternatively activated macrophage (AAM) as early as 7 days after infection of mice in unsurprising." (PMID 32983184, 2020). "Subsequently, we sought to examine the influence of Ss infection on the systemic levels of Type-1 (IFN-γ, TNF-α, and IL-2), Type-17 (IL-17A and IL-22), Type-2 (IL-4, IL-5, and IL-13), regulatory (IL-10) and pro-inflammatory cytokines (IL-1α, IL-1β, IL-6, IL-12, and GM-CSF) in INF and UN individuals." (PMID 33042134, 2020). "As expected, the infection level in the classically stimulated macrophages was significantly lower compared to either non-stimulated or IL-4-treated cells." (PMID 32024293, 2020). "Our results suggested that significant increase in IL‐4 and IFN‐γ productions and inhibited level of IL‐10 might enhance the protective immune response against the infection of H contortus." (PMID 32043596, 2020). "Synthetic peptides of BTV2-VP2 induced significant IL-4 within 12–24 h post-infection (hpi) in PBMCs, whereas those of BTV12 did not, consistent with the bioinformatics prediction." (PMID 33375108, 2020). "Finally, C. psittaci infection induced robust expressions of type Th2 cytokines interleukin (IL)-4 and IL-10, while interferon gamma (IFN-γ) and tumor necrosis factor-α (TNF-α) displayed a significant decrease compared to H9N2 infection alone at 24 hpi." (PMID 32326284, 2020). "Nonetheless, neither specific antibodies, nor increased secretion of IFNγ, IL-4, and IL-10 cytokines, conferred greater protection against infection." (PMID 32916868, 2020). "IL-2 levels significantly decreased at 6 h after infection, increased significantly at 3–6 dpi, and were not significantly different at 30 h; IL-4 levels were increased from 3 dpi to 6 dpi." (PMID 31855175, 2019). "Further, we found the levels of IL-4, IL-10 and IL-13 were not elevated in response to rosiglitazone treatment during super-infection." (PMID 31159430, 2019). "Therefore, we evaluated the expression of NF-κB, TNF-α, IL-8 and IL-4 in CEFs following: (i) infection with GaHV-2, (ii) exposure to PFOS, and (iii) combination of both (exposure to PFOS followed by infection with GaHV-2)." (PMID 31238913, 2019). "Hence, we performed a time course kinetic experiment using BMDMs stimulated with IL-4, IL-13, and a combination of IL-4 and IL-13 (IL-4/IL-13) for alternative activation, followed by Mtb HN878 infection." (PMID 30941122, 2019). "Altogether, this strengthens and confirms previous data, in which CD11c-expressing cells served as a reservoir for pathogen replication, and showed increased infection in the absence of IL-4-signaling via the IL-4Rα chain." (PMID 32039054, 2019).